C9orf72 (C9orf72-SMCR8 complex subunit)
Description:
Acts as a guanine-nucleotide releasing factor (GEF) for Rab GTPases by promoting the conversion of inactive RAB-GDP to the active form RAB-GTP. Acts as a GEF for RAB39A which enables HOPS-mediated autophagosome-lysosome membrane tethering and fusion in mammalian autophagy. Component of the C9orf72-SMCR8 complex where both subunits display GEF activity and that regulates autophagy. As part of the C9orf72-SMCR8-WDR41 (CSW) complex, functions as GEF for RAB8A and RAB39B, thereby promoting autophagosome maturation. As part of the C9orf72-SMCR8 complex, also functions as GTPase activating protein (GAP) for RAB8A and RAB11A in vitro. The C9orf72-SMCR8 complex also acts as a regulator of autophagy initiation by interacting with the ULK1/ATG1 kinase complex and modulating its protein kinase activity. Promotes initiation of autophagy by regulating the RAB1A-dependent trafficking of the ULK1/ATG1 kinase complex to the phagophore which leads to autophagosome formation. Acts as a regulator of mTORC1 signaling by promoting phosphorylation of mTORC1 substrates. Plays a role in endosomal trafficking. May be involved in regulating the maturation of phagosomes to lysosomes (By similarity). Promotes the lysosomal localization and lysosome-mediated degradation of CARM1 which leads to inhibition of starvation-induced lipid metabolism (By similarity). Regulates actin dynamics in motor neurons by inhibiting the GTP-binding activity of ARF6, leading to ARF6 inactivation. This reduces the activity of the LIMK1 and LIMK2 kinases which are responsible for phosphorylation and inactivation of cofilin, leading to CFL1/cofilin activation. Positively regulates axon extension and axon growth cone size in spinal motor neurons. Required for SMCR8 protein expression and localization at pre- and post-synaptic compartments in the forebrain, also regulates protein abundance of RAB3A and GRIA1/GLUR1 in post-synaptic compartments in the forebrain and hippocampus (By similarity). Plays a role within the hematopoietic system in restricting inflammation and the development of autoimmunity (By similarity). [Isoform 1]: Regulates stress granule assembly in response to cellular stress. [Isoform 2]: Does not play a role in regulation of stress granule assembly in response to cellular stress.
Synonyms: DENND9; DENNL72; MGC23980; ALSFTD; FTDALS; FTDALS1
Tractability: Small molecule: a structure with a bound ligand is known. Antibody: UniProt places it where antibodies can reach, with high confidence; its Gene Ontology location is reachable by antibodies, with medium confidence. PROTAC: ubiquitination databases record sites on it; its protein half-life has been measured.
Gene: Protein-coding gene on chromosome 9 (27,535,640 to 27,573,895, reverse strand). Ensembl gene ENSG00000147894.
Subcellular location: Cytoplasm; Nucleus; Cytoplasm, P-body; Cytoplasm, Stress granule; Endosome; Lysosome; Cytoplasmic vesicle, autophagosome; Autolysosome; Secreted; Cell projection, axon; Cell projection, growth cone; Perikaryon; Perikaryon (Isoform 1); Cell projection, dendrite; Presynapse; Postsynapse; Nucleus membrane (Isoform 2)
Subcellular location (Human Protein Atlas): Cytosol; Vesicles; Midbody ring
Gene Ontology:
Molecular function: GTPase activator activity; guanyl-nucleotide exchange factor activity; protein binding; small GTPase binding
Biological process: autophagosome-lysosome fusion; autophagy; axon extension; endocytosis; negative regulation of protein phosphorylation; positive regulation of macroautophagy; regulation of actin filament organization; regulation of autophagosome assembly; regulation of autophagy; regulation of TORC1 signaling; stress granule assembly; late endosome to lysosome transport; regulation of protein localization; regulation of synaptic vesicle cycle
Cellular component: Atg1/ULK1 kinase complex; autolysosome; autophagosome; axonal growth cone; cytoplasm; cytoplasmic stress granule; cytosol; endosome; extracellular region; guanyl-nucleotide exchange factor complex; lysosome; main axon; nuclear membrane; nucleus; P-body; perikaryon; presynaptic cytosol; postsynapse; presynapse; axon; dendrite; glutamatergic synapse; growth cone; hippocampal mossy fiber to CA3 synapse; neuron projection
Genetic constraint (gnomAD): Loss-of-function variants: 13 observed, 20.9 expected, observed/expected ratio (o/e) 0.62, 90% interval 0.4 to 0.99. The upper end of that interval is the gene's LOEUF score, 0.99, which puts it in group 4 of 6, group 1 being the genes least tolerant of losing a copy. Missense variants: 360 observed, 368.36 expected, observed/expected ratio (o/e) 0.98, 90% interval 0.9 to 1.07. Synonymous variants: 131 observed, 125.85 expected, observed/expected ratio (o/e) 1.04, 90% interval 0.9 to 1.2.
Gene-disease validity (ClinGen):
ClinGen rates the evidence that C9orf72 causes each of these diseases.
frontotemporal dementia and/or amyotrophic lateral sclerosis 1 (autosomal dominant): Definitive. Any frontotemporal dementia with motor neuron disease in which the cause of the disease is a mutation in the C9orf72 gene.
Homologues: Orthologues: chimpanzee C9orf72 (99% identical), macaque C9orf72 (99% identical), dog C9orf72 (99% identical), guinea pig C9orf72 (99% identical), rabbit C9orf72 (99% identical), pig C9orf72 (98% identical), mouse C9orf72 (98% identical), rat RGD1359108 (98% identical), tropical clawed frog c1h9orf72 (84% identical), zebrafish C13H9orf72 (73% identical), Caenorhabditis elegans alfa-1 (22% identical).
Diseases named in the same sentence as C9orf72 in open-access papers:
C9orf72 is named in the same sentence as 181 diseases in open-access papers, as found by Europe PMC text mining. Sharing a sentence is not in itself a finding about the gene and the disease. The quoted sentences say what the papers report.
frontotemporal dementia (581 papers, 2012 to 2026). Frontotemporal dementia (FTD) comprises a group of neurodegenerative disorders, characterized by progressive changes in behavior, executive dysfunction and language impairment, as a result of degeneration of the medial prefrontal and frontoinsular cortices. "Repeat expansions of the hexanucleotide GGGGCC in C9orf72 form aberrant phase transitions that have been linked to Amyotrophic Lateral Sclerosis and Frontotemporal Dementia." (PMID 41993388, 2026). "An aberrant six-base repeat in intron 1 of C9orf72 is the most frequent cause of solitary and familial amyotrophic lateral sclerosis and frontotemporal dementia." (PMID 41909467, 2026). "The hexanucleotide (G4C2) repeat expansion in the promoter region of C9orf72 is the most frequent genetic cause of frontotemporal dementia (FTD) and amyotrophic lateral sclerosis (ALS)." (PMID 41024438, 2025). "Large hexanucleotide (GGGCC) repeat expansions in C9orf72 have been identified as the most common monogenic cause of frontotemporal dementia (FTD) and amyotrophic lateral sclerosis (ALS)." (PMID 40138021, 2025). "Innovative preclinical research in 2025 on C9orf72 mutation-associated frontotemporal dementia (FTD) demonstrated that increasing brain omega-3 content extended survival in model organisms and patient-derived cells." (PMID 41515400, 2025). "ALS with frontotemporal dementia (ALS-FTD) is often caused by a polymorphic hexanucleotide repeat expansion (HRE) of GGGGCC (G4C2) in the first intron of the C9orf72 gene from normally less than 30 repeats into the hundreds or thousands, pathologically." (PMID 40002468, 2025). "Pathogenic hexanucleotide repeat expansions in C9orf72 are the commonest genetic cause of frontotemporal dementia and/or amyotrophic lateral sclerosis." (PMID 40138021, 2025). "Carriers of the GGGGCC pathogenic expansion in C9orf72 can develop symptoms of frontotemporal dementia and/or amyotrophic lateral sclerosis, with variable and unpredictable ages at onset." (PMID 40585812, 2025). "Additional ASO therapies are under investigation for other genetically defined forms of ALS, such as those involving FUS and C9orf72 mutations, and are also being explored in Huntington’s disease, Alzheimer’s disease, and frontotemporal dementia." (PMID 40869897, 2025). "Amyotrophic lateral sclerosis (ALS) and frontotemporal dementia (FTD) are neurodegenerative diseases whose most common genetic cause is a hexanucleotide repeat expansion within the C9orf72 gene." (PMID 40663502, 2025). "Whole-genome-sequencing of patients carrying pathogenic C9orf72 expansions was used to consider short-tandem-repeats linked to polyglutamine disorders as potential modifiers of frontotemporal-dementia/amyotrophic-lateral-sclerosis." (PMID 40585812, 2025). "The most frequently observed genetic cause of amyotrophic lateral sclerosis (ALS) and frontotemporal dementia (FTD) is a non-coding hexanucleotide (GGGGCC) repeat expansion in the gene C9orf72." (PMID 39709476, 2024). "Dipeptide repeat proteins are a major pathogenic feature of C9orf72 amyotrophic lateral sclerosis (C9ALS)/frontotemporal dementia (FTD) pathology, but their physiological impact has yet to be fully determined." (PMID 38424324, 2024). "Expansion of G4C2 repeats in the C9orf72 gene causes amyotrophic lateral sclerosis with frontotemporal dementia (C9ALS/FTD), one of the most common forms of ALS." (PMID 38388640, 2024). "The gene C9orf72 harbors a non-coding hexanucleotide repeat expansion known to cause amyotrophic lateral sclerosis and frontotemporal dementia." (PMID 39709476, 2024). "The most prevalent genetic cause of both amyotrophic lateral sclerosis and frontotemporal dementia is a (GGGGCC)n nucleotide repeat expansion (NRE) occurring in the first intron of the C9orf72 gene (C9)." (PMID 38684907, 2024).
frontotemporal dementia (continued). "The abnormal GGGGCC hexanucleotide repeat expansions (HREs) in C9orf72 cause the fatal neurodegenerative diseases including amyotrophic lateral sclerosis and frontotemporal dementia." (PMID 38860430, 2024). "Hexanucleotide repeat expansion in C9orf72 is one of the most common causes of amyotrophic lateral sclerosis and frontotemporal dementia." (PMID 38295729, 2024). "The most common genetic cause of amyotrophic lateral sclerosis (ALS) and frontotemporal dementia (FTD) is a hexanucleotide repeat expansion (HRE) intronic to C9orf72 (C9-ALS/FTD)." (PMID 39421070, 2024). "At the molecular level, the C9orf72 GGGGCC repeat expansion has been linked to both frontotemporal dementia (FTD) and ALS." (PMID 38254109, 2024). "This includes the mutant Htt associated with HD, C9orf72 of amyotrophic lateral sclerosis and frontotemporal dementia (ALS/FTD) and NOP56 of spinocerebellar atrophy type 36 (SCA36)." (PMID 38374466, 2024). "The most common genetic cause of ALS/frontotemporal dementia is an expanded GGGGCC-repeat in the C9orf72 gene." (PMID 37759552, 2023). "The GGGGCC hexanucleotide repeat expansion mutation in the chromosome 9 open reading frame 72 (C9orf72) gene is a major genetic cause of amyotrophic lateral sclerosis and frontotemporal dementia (C9ALS/FTD)." (PMID 38110419, 2023). "The mutation of the C9orf72 gene is also frequently associated with Frontotemporal Dementia (FTD), which unexpectedly shows a strong molecular overlap with ALS." (PMID 37454169, 2023). "Hexanucleotide repeat expansions within C9orf72 are a frequent cause of amyotrophic lateral sclerosis and frontotemporal dementia." (PMID 37317656, 2023). "As another example, the hexanucleotide (GGGGCC) repeat expansion in the non-coding region C9orf72 can cause both frontotemporal dementia (FTD) and/or amyotrophic lateral sclerosis (ALS)." (PMID 38132285, 2023). "Hexanucleotide repeat expansion (HRE) intronic to C9orf72 is the most common genetic cause of frontotemporal dementia (FTD) and amyotrophic lateral sclerosis (ALS)." (PMID 36446586, 2023). "Hexanucleotide repeat expansions in the C9orf72 gene are the most prevalent genetic cause of amyotrophic lateral sclerosis and frontotemporal dementia." (PMID 37308278, 2023). "Nucleotide repeat expansion of GGGGCC (G4C2) in the non-coding region of C9orf72 is the most common genetic cause underlying amyotrophic lateral sclerosis and frontotemporal dementia." (PMID 38129650, 2023). "GGGGCC repeat expansion in the C9orf72 gene causes amyotrophic lateral sclerosis and frontotemporal dementia." (PMID 37717009, 2023). "The expanded hexanucleotide GGGGCC repeat mutation in the C9orf72 gene is the main genetic cause of amyotrophic lateral sclerosis and frontotemporal dementia." (PMID 37717009, 2023). "An intronic GGGGCC repeat expansion in C9orf72 is a common genetic cause of amyotrophic lateral sclerosis and frontotemporal dementia." (PMID 37438085, 2023). "The most common genetic cause of both amyotrophic lateral sclerosis (ALS) and frontotemporal dementia (FTD) has been proven to be a large hexanucleotide repeat expansion (G4C2)n within intron 1 of C9orf72 (C9)." (PMID 34491551, 2022). "Our findings call to mind recent work on translation of G4C2 or TG3C2 repeats from expansions of that cause C9orf72-mediated Amyotrophic lateral sclerosis and frontotemporal dementia (C9 ALS/FTD) and Spinocerebellar ataxia type 36 (SCA36), respectively." (PMID 35904811, 2022). "A repeat expansion in C9orf72 is the major cause of both frontotemporal dementia and amyotrophic lateral sclerosis, accounting for approximately 1 in 12 cases of either disease." (PMID 35314728, 2022). "Genetic causes of FTLD, including MAPT, PGRN and C9orf72 genes, should be excluded; C9orf72 is particularly often related to behavioural variant of frontotemporal dementia, with the presence of motor neuron disease symptoms, which are absent in PSP-F." (PMID 35221993, 2022).
frontotemporal dementia (continued). "Dipeptide repeat (DPR) proteins are aggregation-prone polypeptides encoded by the pathogenic GGGGCC repeat expansion in the C9ORF72 gene, the most common genetic cause of amyotrophic lateral sclerosis and frontotemporal dementia." (PMID 35568435, 2022). "C9orf72 mutations are also a frequent cause of frontotemporal dementia (FTD) which underscores the genetic and pathological overlap with ALS." (PMID 36559296, 2022). "Translation of the hexanucleotide G4C2 expansion associated with C9orf72 amyotrophic lateral sclerosis and frontotemporal dementia (ALS/FTD) produces five different dipeptide repeat protein (DPR) species that can confer toxicity." (PMID 35379876, 2022). "In 2011, a hexanucleotide GGGGCC (G4C2)n repeat expansion in the C9orf72 gene was found to be implicated in frontotemporal lobar degeneration and amyotrophic lateral sclerosis as the most common known genetic cause." (PMID 34912191, 2021). "Subcortical, cerebellar and brain stem regions were also affected in line with observations in pre-symptomatic carriers of mutations in C9orf72, the commonest genetic cause of both amyotrophic lateral sclerosis and frontotemporal dementia." (PMID 34136812, 2021). "A hexanucleotide repeat expansion mutation in the first intron of C9orf72 is the most common known genetic cause of amyotrophic lateral sclerosis and frontotemporal dementia." (PMID 34070550, 2021). "Expansion of GGGGCC (G4C2) repeats in the C9orf72 is the most common genetic cause of ALS with frontotemporal dementia (C9-ALS/FTD)." (PMID 34204190, 2021). "A major cause of familial amyotrophic lateral sclerosis (ALS) and frontotemporal dementia (FTD) spectrum disorder is the hexanucleotide G4C2 repeat expansion in the first intron of the C9orf72 gene." (PMID 34297726, 2021). "Defects in C9orf72 have been associated with the development of amyotrophic lateral sclerosis and frontotemporal dementia (ALS/FTD) but the molecular functions of this protein are still unclear." (PMID 34557489, 2021). "A fifth of frontotemporal dementia cases have autosomal dominant inheritance, most commonly due to hexanucleotide expansions in the chromosome 9 open reading frame 72 (C9orf72), mutations of granulin (GRN), or microtubule‐associated protein tau (MAPT) genes." (PMID 34133849, 2021). "The most frequent genetic cause of amyotrophic lateral sclerosis and frontotemporal dementia is a G4C2 repeat expansion in the C9orf72 gene." (PMID 34161229, 2021). "An expansion of hexanucleotide GGGGCC (G4C2) repeat within the first intron of C9orf72 gene is the most common cause of familial ALS as well as frontotemporal dementia (FTD), commonly termed as C9-ALS/FTD." (PMID 33129345, 2020). "A large intronic hexanucleotide repeat expansion (GGGGCC) within the C9orf72 (C9orf72-SMCR8 Complex Subunit) locus is the most prevalent genetic cause of both Frontotemporal Dementia (FTD) and Motor Neuron Disease (MND)." (PMID 32894207, 2020). "Pathogenic mutation in C9orf72 is the most common cause of frontotemporal dementia and amyotrophic lateral sclerosis." (PMID 32100453, 2020). "GGGGCC repeat expansion in C9orf72 is the most common genetic cause in both frontotemporal dementia (FTD) and amyotrophic lateral sclerosis (ALS), two neurodegenerative disorders in association with aging." (PMID 32100453, 2020). "Repeat expansion in C9orf72 causes amyotrophic lateral sclerosis and frontotemporal lobar degeneration." (PMID 31642962, 2020). "A C9orf72 repeat expansion is the most common genetic cause of frontotemporal dementia (FTD) and amyotrophic lateral sclerosis." (PMID 33168090, 2020). "Expansion of an intronic (GGGGCC)n repeat region within the C9orf72 gene is a main cause of familial amyotrophic lateral sclerosis and frontotemporal dementia (c9ALS/FTD)." (PMID 32620797, 2020). "The hexanucleotide repeat expansion in the C9orf72 gene is also associated with frontotemporal dementia (FTD)." (PMID 33096681, 2020).